TPH1 (tryptophan hydroxylase 1)
Diseases named in the same sentence as TPH1 in open-access papers (continued):
Sharing a sentence is not in itself a finding about the gene and the disease.
colorectal cancer (8 papers, 2019 to 2025). A primary or metastatic malignant neoplasm that affects the colon or rectum. "Silencing TPH1 expression slowed down tumor growth in an established mouse model, whereas treatment with TPH1 inhibitor alleviated tumor progression in an azoxymethane/dextran sodium sulphate (AOM/DSS)-induced colorectal cancer (CRC) mouse model." (PMID 39309474, 2024). "Following assessment of several human colorectal cancer cell lines for TPH1 mRNA expression we identified Colo320 cells as being suitable for use." (PMID 36947541, 2023). "In colorectal cancer, IL-2 activates TPH1-5-HTP-AhR signaling in the tumor microenvironment to induce CD8+ T cell exhaustion in tumor tissues." (PMID 36703779, 2022). "The NLRP3 inflammasome activates IL1β, which stimulates tryptophan hydroxylase 1 (TPH1, gene coding the 5-HT biosynthesis rate-limiting enzyme) transcription to increase 5-HT production in colorectal cancer cells, forming a positive feedback loop between 5-HT and NLRP3 signaling." (PMID 38523155, 2024). "Moreover, TPH-1 knockdown or 4-chloro-DL-phenylalanine (a TPH-1 inhibitor) treatment can retard tumor growth in mice models of colorectal cancer." (PMID 35473609, 2022). "Furthermore, in colorectal cancer, intestinal enterochromaffin (EC) cells and certain immune cells convert a portion of tryptophan (Trp) to 5-hydroxytryptamine (5-HT) via tryptophan hydroxylase 1 (TPH1), collectively exacerbating Trp starvation in the tumor microenvironment." (PMID 41488637, 2025). "Excessive production of serotonin, as a result of upregulated expression of serotonin biosynthesis rate-limiting enzyme tryptophan hydroxylase 1 (TPH1), contributes to NLRP3 inflammasome activation via serotonin receptor HTR3A and the acceleration of colorectal cancer development." (PMID 35954387, 2022).
diabetes (8 papers, 2010 to 2022). "In Tph1 knockout mice, the concentration of islet 5-HT was reduced by 10-fold, and diabetes developed as early as 14 days after birth." (PMID 26187948, 2015). "In this regard, a study with HFD-induced diabetes in mice has already shown that oral administration of the TPH1 inhibitor LP533401 led to an improvement of peripheral insulin sensitivity and glucose tolerance as well as a reduction of hyperglycemia and hyperlipidemia." (PMID 35742878, 2022). "Several abnormalities have been reported in Tph1 (−/−) mice such as diabetes, decreased cardiac function under anesthesia and anemia that could potentially contribute to behavioral differences." (PMID 23516593, 2013). "Several phenotypes have been reported in Tph1 (−/−) mice such as mild anemia, decreased neutrophil recruitment to inflammatory sites, diabetes, in particular during pregnancy, and cardiopathy which could potentially lead to behavioral deficits in offspring of Tph1 (−/−) mice." (PMID 23516593, 2013). "Thus, TPH1 seems not to contribute to brain 5-HT biosynthesis but it cannot be ruled out that impaired TPH1 activity leads to psychiatric illness due to metabolic disorders, such as diabetes or impaired liver function." (PMID 20126463, 2010).
Insulin resistance (8 papers, 2018 to 2026). Increased resistance towards insulin, that is, diminished effectiveness of insulin in reducing blood glucose levels. "Mice on a high fat diet are not only heavier but have increased insulin resistance and non-alcoholic fatty liver disease that can be reduced pharmacologically with inhibitors of Tph1 or genetically in mice deficient in Tph1." (PMID 34769340, 2021). "Both WT and Tph1 MKO mice exhibited similar body weight, glucose tolerance and insulin resistance." (PMID 40451926, 2025). "First, we showed that reconstitution of KitW-sh/W-sh mice with Tph1+/+ mast cells increased weight gain and insulin resistance, while Tph1−/− mast cells did not." (PMID 31974364, 2020). "We also determined the role of serotonin in the tryptamine and phenethylamine-induced insulin resistance and revealed the blockade of serotonin synthesis using a chemical inhibitor of TPH1 LX-1031 did not affect the inhibitory effects of acute treatment of tryptamine on glucose tolerance." (PMID 37591886, 2023).
Hepatic steatosis (7 papers, 2018 to 2026). Steatosis is a term used to denote lipid accumulation within hepatocytes. "A similar protection against HFD-induced hepatic steatosis was also observed in mice ablated for TPH1 or 5-HT2B in adipocytes (adiponectin-cre; Tph1fl/fl or Htr2bfl/fl) or mice genetically deleted for the 5-HT3a receptor (Htr3a-/-) 225,228." (PMID 41424854, 2026). "It has been further shown that eliminating gut-derived serotonin by intestine-specific Tph1-KO markedly ameliorates hepatic steatosis, revealing a close relationship between gut-derived serotonin and hepatic lipid metabolism." (PMID 39926388, 2025). "In order to identify the relevant metabolic pathways that prevent hepatic steatosis in Tph1 GKO mice, we performed gene expression analyses for an extensive array of metabolic markers." (PMID 30446669, 2018). "Total body Tph1-KO mice fed an HFD showed protection against hepatic steatosis." (PMID 39926388, 2025). "Based on this understanding, gut-derived serotonin exacerbates hepatic steatosis through direct actions on liver, and gut TPH1–liver 5-HTR2A axis might be a potential drug target for anti-MASLD therapies." (PMID 39926388, 2025). "As such, we thoroughly examined the systemic metabolic phenotype of HFD-fed Tph1 GKO mice to evaluate whether increased energy expenditure improved hepatic steatosis indirectly by reducing FA influx in the liver." (PMID 30446669, 2018). "As gut-specific tryptophan hydroxylase 1 (Tph1) knockout mice and liver-specific Htr2a knockout mice are resistant to high-fat diet (HFD)-induced hepatic steatosis, the gut TPH1-liver-HTR2A axis is a promising drug target for NAFLD." (PMID 35765850, 2022). "In order to investigate the functional role of GDS in hepatic steatosis in vivo, we generated gut-specific Tph1 knockout (KO) (Villin-Cre+/–; Tph1flox/flox, herein named Tph1 GKO) mice and induced hepatic steatosis with 8 weeks of HFD feeding." (PMID 30446669, 2018). "In the present study, we demonstrated that HFD-fed Tph1 GKO mice are protected against hepatic steatosis without affecting systemic energy homeostasis." (PMID 30446669, 2018). "Taken together, systemic energy metabolism does not seem to play a role in ameliorating HFD-induced hepatic steatosis in Tph1 GKO mice." (PMID 30446669, 2018). "Moreover, a selective HTR2A antagonist showed efficacy in improving hepatic steatosis as predicted by Tph1 GKO mice and Htr2a LKO mice phenotypes in HFD-induced hepatic steatosis." (PMID 30446669, 2018). "Taken together with data from Tph1 GKO and Htr2a LKO mice, we have identified a previously unknown enterohepatic signaling pathway for hepatic steatosis mediated by GDS and hepatic HTR2A." (PMID 30446669, 2018). "As inhibition of GDS synthesis does not prevent hepatic steatosis in Tph1 GKO upon MCD diet, liver FA outflux is unlikely to mediate the GDS effects on liver." (PMID 30446669, 2018). "Thus, SLZBS may mitigate hepatic steatosis by inhibiting the expressions of HTR2A in the liver and TPH-1 in the small intestine as well as by reducing the levels of 5-HT in the liver and small intestine." (PMID 38720776, 2024). "However, when hepatic steatosis was induced with 8 weeks of HFD feeding, hepatic lipid droplet accumulation, NAFLD activity score (NAS), and hepatic TG levels were dramatically reduced in the liver of HFD-fed Tph1 GKO mice 28, indicating that reduced GDS production inhibits the progression of NAFLD." (PMID 30446669, 2018). "Both gut-specific Tph1 knockout mice and liver-specific Htr2a knockout mice are resistant to HFD-induced hepatic steatosis, without affecting systemic energy homeostasis." (PMID 30446669, 2018). "Here we demonstrate that inhibition of GDS synthesis by Tph1 GKO mice ameliorates hepatic steatosis independent of systemic energy homeostasis and Htr2a LKO mice revealed a phenocopy of Tph1 GKO mice." (PMID 30446669, 2018).
Hepatic steatosis (continued). "Both Tph1 GKO and Htr2a LKO mice were effective only in HFD-induced liver steatosis without altering systemic energy homeostasis which suggest that blocking enterohepatic signaling pathways mediated by GDS and HTR2A represses TG accumulation in the liver." (PMID 30446669, 2018).
pulmonary arterial hypertension (7 papers, 2011 to 2025). Pulmonary arterial hypertension (PAH) is a group of diseases characterized by mean pulmonary artery pressure >20 mmHg and elevated pulmonary arterial resistance leading to right heart failure. "In experimental pulmonary hypertension (PH), pulmonary expression of tryptophan hydroxylase‐1 (TPH1), the rate limiting enzyme in 5‐HT synthesis, and plasma 5‐HT are increased." (PMID 36200294, 2022). "Scientists at Karos Pharmaceuticals have reported that spirocyclic TPH1 inhibitors such as telotristat ethyl can be used to treat Pulmonary Arterial Hypertension (PAH) and Inflammatory Bowel Disease (IBD)." (PMID 35684355, 2022). "The percentage of SERT, 5HT2A, TPH1, ERK1/2, pERK1/2 positive areas in the control, degenerative mitral valve disease (DMVD) and degenerative mitral valve disease with pulmonary hypertension (DMVD+PH) groups." (PMID 33426031, 2020). "While genetic and pharmacologic inhibition of tryptophan hydroxylase 1 (TPH1) has protective effects in adult models of pulmonary hypertension (PH), our results suggest that tph1 inhibition would not be beneficial in neonates with PH associated with BPD." (PMID 36200294, 2022).
inflammatory bowel disease (6 papers, 2014 to 2025). A spectrum of small and large bowel inflammatory diseases of unknown etiology. "Indeed, decreased TRP concentration and increased IDO1 and tryptophan hydroxylase 1 (TPH1) enzymatic activities were detectable in plasma samples concomitant to precancerous lesion (high grade-adenomas) or in association to risk factors (inflammatory bowel diseases)." (PMID 33178611, 2020). "This study underscores the pivotal role of serotonin metabolism in pediatric inflammatory bowel disease pathogenesis, with elevated TPH1 expression in the inflamed transverse colon and reduced MAOA expression in regions like the ileum and descending colon driving an inflammatory imbalance." (PMID 41465348, 2025). "Crohn’s disease (also known as regional enteritis) is a type of inflammatory bowel disease that affects any part of the gastrointestinal tract from the mouth to the anus, and may be expressed as peripheral TPH1 dysfunction and IDO activation, induced by intestinal inflammation." (PMID 25540092, 2014). "Reports originating from animal models on inflammatory bowel disease (IBD), SERT KO, TPH1 KO models, and pathogen invasion studies as well as clinical data from Crohn’s disease patients have collectively contributed to this view." (PMID 33807994, 2021).
melanoma (6 papers, 2018 to 2025). A malignant, usually aggressive tumor composed of atypical, neoplastic melanocytes. "We developed an improved experimental model by implanting syngeneic liver-targeted melanoma cells that were genetically engineered to produce 5-HT through the expression of the enzyme tryptophan hydroxylase type 1 (Tph1) in wild-type C57BL/6 mice." (PMID 40885776, 2025). "Lastly, TPH1, involved in 5-methoxytryptophan synthesis, exhibited increased levels in melanoma cells compared to tumor- infiltrating lymphocytes." (PMID 37844995, 2023). "Ultraviolet rays (UVR) also inhibit TPH1 expression in squamous cell carcinoma C1-4 cells and human melanoma cells." (PMID 34360837, 2021). "This is consistent with previous reports on the capability of human melanoma cells to produce and metabolize melatonin and the expression of TPH1 in human melanoma skin biopsies and rodent melanomas." (PMID 30487387, 2018). "TPH1 transcriptomes of the expected sequence were found in skin samples containing normal skin and basal cell carcinoma, cultured melanocytes, melanoma cell lines, normal keratinocytes, squamous cell carcinoma cells, and fibroblasts (skin and dermal follicles)." (PMID 34360837, 2021). "Acute myeloid leukemia/TPH1; Non-small-cell lung cancer/A549; Hepatoma/Hepa-1c1c7; Pancreatic cancer/PATU-8988 and PANC-1; Melanoma/A375." (PMID 34589492, 2021).
breast tumor (5 papers, 2009 to 2021). "Our current efforts are centered on conditionally targeting SLC6A4 and the genes encoding TPH1 and each of the 14 5-HT receptors in human breast tumor cell lines to learn whether loss of each gene phenocopies the effect of selective serotonergic antagonists of their encoded molecular targets." (PMID 28404880, 2017). "Studies have revealed that 5-HTR2A is expressed in the MCF-7 breast tumor cell line, whereas TPH1 and SERT are expressed in the MCF-7, MB-MDA-231, and T47D breast tumor cell lines." (PMID 34073226, 2021). "Serotonin biosynthetic capacity was analyzed in human breast tumor tissue microarrays using immunohistochemistry for tryptophan hydroxylase 1 (TPH1)." (PMID 19903352, 2009). "Antibodies specific to SERT, TPH1, or 5-HT were used to learn whether they are present in human breast tumor cell lines, breast tumors, and their xenografts." (PMID 34073226, 2021). "To learn whether TPH1 and 5-HT were expressed in breast tumor cell lines we used immunofluorescence (IF) staining with antibodies that bind to each of these molecules as well as to SERT." (PMID 28404880, 2017). "Indeed transcripts encoding TPH1, SERT and the 5-HT receptors declined with passage number in between 40%–90% of 72 breast tumor cell lines for which data was available at the time of plating the tumor cells, and after each of 2 passages." (PMID 27447971, 2016). "TPH1 and 5-HT were also present in the cells comprising tumorspheres derived from the HCC1954 breast tumor cell line and those of its xenografts using IF." (PMID 34073226, 2021). "We assayed the activity of 7 concentrations of compounds known to be selective for TPH1, SERT or each of 9 of the 14 human 5-HT receptors in HCC1954 breast tumor cells to establish their half maximal inhibitory concentration (IC50) in sphere-forming assays." (PMID 28404880, 2017). "The serotonergic system including TPH1, SERT and numerous 5-HT receptors are also expressed in human breast tumor cell lines and breast tumors." (PMID 27447971, 2016). "TPH1 and 5-HTR1A, -1B, -2B, -4, 5A, and -7 are also expressed in human breast tumors." (PMID 34073226, 2021). "shRNAs targeting transcripts encoding TPH1, SERT and many of the 5-HT receptors statistically significantly dropped out during the propagation of the breast tumor cell lines in vitro (data not shown)." (PMID 28404880, 2017). "Notably, selective antagonists of TPH1, SERT, and a subset of 5-HTRs (5-HT1B, 5-HT1D, 5-HT2A, 5-HT2B, 5-HT2C, 5-HT5A, and 5-HT6) all reduced tumor cell viability and tumorsphere-forming cell frequency in all the breast tumor cell lines." (PMID 34073226, 2021).
ischemic stroke (5 papers, 2015 to 2024). A stroke disorder caused by obstruction of blood flow to the brain, due to thrombotic (local blood clot formation) or embolic (due to a blood clot or other material traveling from another site) event. "We present data demonstrating associations between ischemic stroke and variants of four genes (TPH1, IDO1, KYAT1 and AADAT) encoding enzymes of Trp metabolism." (PMID 34680558, 2021). "In the in vivo MCAO (middle cerebral artery occlusion) rat model of ischemic stroke, TPH1 was up-regulated in brain tissue of the animals 4 days after artery occlusion." (PMID 34680558, 2021). "Upregulation of Tph1 and downregulation of Olr883 after acupuncture treatment indicate that the therapeutic effect of acupuncture for ischemic stroke may be closely related to the suppression of poststroke depression and regulation of olfactory transduction." (PMID 25861363, 2015). "Upregulation of Tph1 and downregulation of Olr883 indicated that the therapeutic effect of acupuncture for ischemic stroke may be closely related to the suppression of poststroke depression and regulation of olfactory transduction." (PMID 25861363, 2015). "Furthermore, we also wished to learn whether changes are detectable in the expression of TPH1, TPH2, IDO1, KYAT1 and AADAT genes in peripheral blood samples (PBS) of ischemic stroke patients during the course of the disease." (PMID 34680558, 2021).
Sepsis (5 papers, 2017 to 2026). Sepsis is defined as life-threatening organ dysfunction caused by a dysregulated host response to infection. "To test the hypothesis that fluoxetine-mediated protection from sepsis was dependent on its actions on peripheral serotonin, we first measured susceptibility of Tph1−/− mice challenged with polymicrobial sepsis." (PMID 39951524, 2025). "Unexpectedly, we found that 100% of Tph1−/− mice treated with fluoxetine were protected from sepsis-induced mortality, while ~50% of vehicle-treated infected Tph1−/− mice succumbed to the challenge." (PMID 39951524, 2025). "In order to explore the role of peripheral 5-HT in sepsis, Tph1−/− mice were constructed and CLP was performed to induce sepsis." (PMID 35111753, 2021). "Interestingly, mice with a tryptophan hydroxylase one knockout (TPH1-KO)—TPH1 is the rate-limiting enzyme for the endogenous production of 5-HT in the periphery—that have low levels of 5-HT in the heart, exhibited lower mortality than WT mice with sepsis." (PMID 34070090, 2021).